USP7 (ubiquitin specific peptidase 7)
Diseases named in the same sentence as USP7 in open-access papers (continued):
Sharing a sentence is not in itself a finding about the gene and the disease.
melanoma (continued). "This study demonstrated that TIP60 and USP7 downregulation decreases ac-DNMT1 protein levels, which increased the amount of DNMT1 and significantly influenced stage IV melanoma disease outcomes." (PMID 34572918, 2021). "Among stage IV melanoma, patients with low ac-DNMT1 protein levels showed significantly lower USP7 protein levels compared to patients with high ac-DNMT1 (p < 0.0001)." (PMID 34572918, 2021). "However, the role of USP7 and its therapeutic value for melanoma remain unclear." (PMID 34469054, 2021). "Cells lacking USP7 show an increased susceptibility to BRAF inhibitors, which makes this DUB a good therapeutic target in melanoma in combination with existing treatments." (PMID 35884430, 2022). "Additionally, we identified the positive correlations between TIP60/USP7 and ac-DNMT1 protein levels in stage IV melanoma metastasis." (PMID 34572918, 2021). "We found that the expression of the USP7 protein was increased in melanoma tissues compared with normal tissue by immunohistochemistry." (PMID 33869052, 2021). "Thus, USP7 recruiting PRC2 complex to suppress the expression of FOXO1 can protect melanin tumors from chemical toxicity, thus promoting the progression of melanoma." (PMID 33849069, 2021). "Interestingly, we found that FOXK1 could also physically interact with USP7 and the PRC2 complex in A375 melanoma cells (data not shown), suggesting that USP7 and PRC2 may share similar transcription factors and thus respond to the same signal pathways." (PMID 33849069, 2021).
leukemia (18 papers, 2017 to 2024). A malignant (clonal) hematologic disorder, involving hematopoietic stem cells and characterized by the presence of primitive or atypical myeloid or lymphoid cells in the bone marrow and the blood. "Overall, the RNA-seq analysis supports our previous finding that USP7 is implicated in the negative regulation of TAL1-dependent leukemia growth." (PMID 35205126, 2022). "Thus, the precise mechanism of USP7 to drive the NOTCH association leukemia signature will need to be carefully examined in future studies." (PMID 35205126, 2022). "Likewise, USP7 loss-of-function mutations have been detected in pediatric leukemias." (PMID 36342772, 2022). "One should silence or inhibit USP7 substantially to block leukemia due to a potential happloinsufficient tumor suppressor role of USP7 in some disease contexts." (PMID 36490346, 2022). "Together, these findings demonstrate that USP11 and USP7 form an oncogenic complex with LCK in leukemia." (PMID 36490346, 2022). "Our present study identifies a previously unidentified regulatory mechanism of the U2 component SF3B1 in pediatric leukemia via USP7 activity and protection against degradation." (PMID 35061527, 2022). "Usp7 knockout relieves leukemia burden as demonstrated by reduced spleen weight coupled to prolonged survival, an effect that is further enhanced upon mouse treatment with DXM." (PMID 36490346, 2022). "Posttranslational regulation of splicing factors via deubiquitination by USP7 contributes to their high protein levels in leukemia." (PMID 35061527, 2022). "As previously observed in leukemia, USP7 depletion in SyS resulted in the partial disassembly of the ncPRC1 complex, as illustrated by the marked decrease in interactions between RING1B and RYBP in the SyS cell line HSSYII." (PMID 33361335, 2021). "Although the induction of NOTCH1 degradation may play a major role, we could not rule out the possibility that other USP7 substrates also contribute to the anti-leukemia effects upon USP7 inhibition." (PMID 30370059, 2018). "In contrast, much fewer human leukemia cells were detected in the USP7-depleted mice." (PMID 30370059, 2018). "USP7 regulates human terminal erythroid differentiation by stabilizing GATA1, providing a certain treatment for leukemia." (PMID 31114498, 2019). "Almost at the same time, researchers found USP7 can bind several oncogenes by interacting and stabilizing NOTCH1 and JmjC Domain-Containing Protein 3 (JMJD3) in order to control leukemia growth." (PMID 31114498, 2019). "P22077, a dual inhibitor of USP7/USP47, overcomes tyrosine kinase inhibitor resistance and eradicates leukemia stem/progenitor cells in chronic myelogenous leukemia through inhibiting its novel substrate Y-box binding protein 1 (YB-1) deubiquitination and suppresses DNA damage repair." (PMID 35301297, 2022). "The effects of USP7 on RNF6 protein were further recapitulated in MM and leukemia cell lines." (PMID 35926709, 2022). "Furthermore, Usp7 can deubiquitinate PTEN to exclude it from the nucleus 28, facilitating PI3K-mTOR signaling in leukemia cells." (PMID 35673573, 2022).
cervical carcinoma (15 papers, 2019 to 2025). A carcinoma arising from either the exocervical squamous epithelium or the endocervical glandular epithelium. "In cervical cancer, USP7 is reported to physically associate with the MRE11-RAD50-NBS1 (MRN)—mediator of DNA damage checkpoint protein 1 (MDC1) complex, enabling DNA repair through the stabilization of MDC1." (PMID 36186590, 2022). "Increased USP7 levels seem to enhance the survival rate of cervical cancer cells through MDC1 stabilization and consequently improve resistance to DNA damage." (PMID 41157055, 2025). "Metadherin (MTDH) and ubiquitin specific protease 7 (USP7) have been identified to involve in the tumorigenesis of cervical cancer (CC)." (PMID 38625581, 2024). "Previous studies have demonstrated that abnormal USP7 expression plays an important role in the pathogenesis of inflammatory responses, and nasopharyngeal, lung, and cervical cancers." (PMID 37199589, 2023). "For instance, USP7 has been found to be upregulated in many cervical carcinomas, where its expression positively correlates with that of MDC1, as well as with histological tumor grade." (PMID 32850836, 2020). "USP7 maintains DNA damage response and promotes cervical cancer, and is positively correlated with poor survival rate in patients with cervical cancer." (PMID 31114498, 2019). "USP7 promotes cervical cancer cell survival and confrere cellular resistance to genotoxic insults via the stabilization of MDC1." (PMID 31114498, 2019). "USP7 can also maintain DNA damage response and promote cervical cancer, and high USP7 expression is positively correlated with poor survival in patients with cervical cancer." (PMID 37762082, 2023). "USP7 was demonstrated to regulate the stability of HPV16 E7 and inhibition of USP7 reduced the proliferation, migration and invasion of HPV16+ cervical cancer cells." (PMID 40011575, 2025). "Inhibition of USP7 with the compounds GNE-6640 or GNE-6776, however, destabilizes MDC1, as well as sensitizes cervical cancer cells to ionizing radiation-induced genotoxic insult." (PMID 32850836, 2020). "USP7 was also found to extend the half-life of CDC25A by circumventing turnover, which stabilized CDC25A and enhanced resistance to DNA-damaging agents in cervical cancer." (PMID 36694209, 2023). "Notably, overexpressed USP7 was positively correlated with the expression of MDC1 and worse survival for patients with cervical cancer." (PMID 36694209, 2023).
glioblastoma (13 papers, 2020 to 2025). The most malignant astrocytic tumor (WHO grade IV). "Taken together, these data identify USP7 as a key regulator of MGMT stability in the nucleus of glioblastoma (GBM) cells by counteracting K48-linked ubiquitination, offering mechanistic insights into MGMT regulation." (PMID 40835840, 2025). "Immunohistochemistry and western blotting confirmed that USP7 was significantly upregulated in glioblastoma samples." (PMID 34556124, 2021). "USP7 inhibitors can induce apoptosis in glioblastoma cells by promoting the ubiquitination of ARF4." (PMID 39767641, 2024). "Quantitative analysis of IF staining revealed a positive correlation between USP7 and MGMT expression levels (p < 0.01, n = 62 glioblastoma samples)." (PMID 40835840, 2025). "MGMT expression was positively correlated with USP7 levels in GBM (grade IV) tissues, while both markers exhibited low expression in adjacent normal tissues (p < 0.01, n = 31 paired glioblastoma samples)." (PMID 40835840, 2025). "We generated hybrid co-culture models of brain organoids with four GFP+ CNS tumor cell lines, two of them representing glioblastoma (LN18 and U343-MG), and the other two representing embryonal CNS tumors (USP7-ATRT and USP13-Med)." (PMID 39599878, 2024). "In glioblastoma (GBM), TRAF4 regulates caveolin 1 (CAV1) stability, and drives GBM cell stemness and temozolomide resistance by blocking ZNRF1-mediated ubiquitination and promoting USP7-mediated deubiquitination." (PMID 36765039, 2023).
Hao-Fountain syndrome (13 papers, 2021 to 2026). "Hao-Fountain syndrome (HAFOUS) is a rare neurodevelopmental disorder caused by pathogenic variants in the USP7 gene." (PMID 41555921, 2025). "The distribution analysis of missense and nonsense mutations linked to Hao-Fountain syndrome reveals that the pathogenic variants are dispersed throughout the USP7 protein." (PMID 40166258, 2025). "Our results offer the first insight into the causes of USP7 malfunction in Hao-Fountain syndrome and provide a foundation for the development of effective diagnostic and treatment strategies in the future." (PMID 40982686, 2025). "A recent study introduced a severity score specific to Hao-Fountain syndrome and showed that pathogenic variants located in the catalytic domain of the USP7 protein are associated with more severe outcomes." (PMID 40166258, 2025). "Our results offer the first insight into the causes of USP7 malfunction in Hao-Fountain syndrome and provide a foundation for the development of effective treatment strategies in the future." (PMID 40166258, 2025). "Our study confirms that nanopore sequencing enables reliable detection of the Hao-Fountain syndrome methylation episignature, alongside pathogenic USP7 variants, within a single assay." (PMID 41555921, 2025). "Although USP7 has been extensively studied in relation to cancer, Hao-Fountain syndrome variants provide unique mechanistic insights into the enzyme’s functions." (PMID 40982686, 2025). "Variants associated with Hao-Fountain syndrome are dispersed throughout the USP7 protein, with a majority affecting the catalytic domain." (PMID 40166258, 2025). "In summary, our comprehensive study of the functional impact of pathogenic variants associated with Hao-Fountain syndrome underscores the complex interplay between structural integrity, enzymatic activity, and allosteric modulation of the USP7 enzyme." (PMID 40166258, 2025). "Hao-Fountain syndrome is a rare neurodevelopmental disorder caused by mutations in the de-ubiquitinating enzyme USP7 (Ubiquitin Specific Protease 7)." (PMID 40166258, 2025). "Pathogenic variants in USP7 [also called Herpes virus-associated ubiquitin-specific protease 7 (HAUSP)] lead to Hao-Fountain Syndrome." (PMID 39135741, 2024). "In this paper, we reported two variants c.2697A > C and c.3305A > C in USP7 by WES analysis in Chinese patients with Hao-Fountain syndrome." (PMID 38229971, 2024). "Repeat testing, but now with whole-exome sequence (WES) analysis, revealed a pathogenic variant of the USP7 gene, prompting the diagnosis of Hao-Fountain syndrome." (PMID 37849578, 2023). "These two disorders share many disease manifestations with Hao-Fountain syndrome, further suggesting that the USP7-deficiency-induced patient phenotypes are caused by aberrant endosomal sorting." (PMID 33335288, 2021). "Furthermore, we determine the high-resolution crystal structure of the TRAF/MAGEL2 complex and identify Hao-Fountain syndrome-linked mutations in USP7 that disrupt USP7/MAGEL2 complex formation in vitro and in cells." (PMID 42094436, 2026). "Taken together, these findings suggest that both loss-of-function and gain-of-function mutations can result in Hao-Fountain syndrome; however, other compensatory mechanisms may contribute to the regulation of abnormal USP7 activity in cells." (PMID 40982686, 2025). "The precise molecular mechanisms underlying Hao-Fountain syndrome and the impact of these pathogenic variants on USP7’s function remain unknown." (PMID 40166258, 2025). "This is particularly interesting, as heterozygous loss-of-function variants of USP7 are the cause of Hao-Fountain syndrome (HAFOUS [MIM: 616863]), a neurodevelopmental disorder that clinically manifests developmental delay/intellectual disability, autism spectrum disorder, muscular hypotonia." (PMID 38908375, 2024).
Hao-Fountain syndrome (continued). "Deletions, truncating and missense variants of USP7 have been associated with the Hao-Fountain syndrome (OMIM 616863), characterized by speech delay, autistic spectrum disorder, attention-deficit hyperactivity disorder, sleep disturbances and gastroesophageal reflux disease." (PMID 34621295, 2021). "Hao-Fountain syndrome (HAFOUS) is a rare neurodevelopmental disorder caused by mutations in the ubiquitin-specific protease 7 (USP7) gene for endosomal recycling." (PMID 37849578, 2023). "The involvement of USP7 in the endosomal protein recycling pathway led to the identification of Hao-Fountain syndrome in 2015 with only six patients." (PMID 40166258, 2025). "It is conceivable that using specific inhibitors and activators of USP7 could offer promising personalized treatment strategies for Hao-Fountain syndrome in the future." (PMID 40166258, 2025). "Hao-Fountain syndrome (HAFOUS) is a rare neurodevelopmental disorder caused by pathogenic variants in the USP7 gene (Ubiquitin-Specific-Processing Protease 7; OMIM #602519) or by chromosomal deletions encompassing USP7." (PMID 41555921, 2025). "Since Hao-Fountain syndrome is caused by heterozygous mutations in the USP7 gene, conceivably, activation of the WT USP7 could compensate for the non-activatable mutant copy." (PMID 40166258, 2025).
liver cancer (13 papers, 2020 to 2025). An epithelial or non-epithelial malignant neoplasm that arises from the liver. "In liver cancer, PROX1 can also enhance the stability of p65 by binding USP7 to affect angiogenesis in liver cancer cells." (PMID 35875077, 2022). "More recently, studies in liver cancer found that the deubiquitinating enzyme USP7 stabilizes TRIP12, which leads to constitutive p14ARF ubiquitination and degradation, thereby promoting the growth of liver cancer cells." (PMID 33963176, 2021). "In summary, our study is the first to report the potential of USP7 inhibitor P22077 therapy for liver cancer." (PMID 32002017, 2020). "Inhibition of the USP7 by P5091 disrupts a positive feedback loop involving PRDM1-mediated upregulation of FGL1, thereby enhancing CD8+ T cell activity and suppressing liver cancer growth; combined USP7 and LAG3 blockade demonstrates superior antitumor efficacy compared to LAG3 inhibition alone." (PMID 41359051, 2025). "Previous evidence showed that USP7 was increased in HBV-related liver cancer." (PMID 35571490, 2022). "Therefore, we suspect that the lethal effect of P22077 on liver cancer cells by inhibiting USP7 deubiquitinating of H3, the specific mechanism remains to be further studied." (PMID 32002017, 2020). "Usp7 knockout in mouse cause embryonic lethality at embryonic days (E) 6.5–7.5, while in human USP7 shows an oncogenic role in neoplastic diseases such as NSCLC, human prostate and liver cancers." (PMID 32531973, 2020). "In addition, reported data supports that USP7 can be used as a new independent prognostic factor for liver cancer." (PMID 32002017, 2020). "USP22, USP14, USP10, USP13, USP7, USP2, and USP8, liver cancer-related DUBs, have also been reported to have related small molecule inhibitors, but the research and development are not mature enough." (PMID 35875077, 2022). "Clinical data were analyzed to determine the effect of USP7 and YY1 on liver cancer." (PMID 37408047, 2023). "Moreover, USP7 and YY1 expression levels were positively correlated with the clinical stage of liver cancer in TCGA." (PMID 37408047, 2023).